NPY (neuropeptide Y)
Diseases named in the same sentence as NPY in open-access papers (continued):
Sharing a sentence is not in itself a finding about the gene and the disease.
depression (continued). "Alternatively, disruptions in systems such as leptin and NPY, which are involved in hunger and satiety, may cause schizophrenia and depression, while simultaneously predisposing patients of these disorders to behavioral risk factors for metabolic syndrome such as poor diet and sedentary lifestyle." (PMID 25762938, 2015). "Neuropeptides include neuropeptide Y (NPY) which is involved in regulation of stress and depression." (PMID 40260016, 2025). "Studies based on the antidepressant effect provide strong evidence of NPY system alterations in stress response, depression pathophysiology, and suicide." (PMID 40636521, 2025). "GAL and its receptors can also interact with noradrenaline, neuropeptide Y, brain-derived neurotrophic factor, and dopamine to regulate depression." (PMID 40048451, 2025). "Along with that, increased NPY levels have been found in the cerebrospinal fluid (CSF) of patients with severe depression." (PMID 39585059, 2024). "In animal models of depression, decreased expression of NPY in the HIPP and hypothalamus and reduced levels of NPY in the HIPP have been observed." (PMID 38397400, 2024). "The involvement of NPY in the pathogenesis of depression is confirmed by the differential expression of the neuropeptide in various animal models of depression." (PMID 39585059, 2024). "The role of NPY in the development of depression, posttraumatic stress disorder, and chronic pain syndrome has been widely studied." (PMID 39585059, 2024). "Previous research showed that NPY expression in the INF is activated by testosterone only in male animals and testosterone deficiency is accompanied by a higher incidence of depression, especially in males after midlife." (PMID 38263257, 2024). "Data also support the involvement of NPY in migraine and depression, showing that the pharmacological modulation of NPY receptors, such as Y2R and Y5R, displays antidepressant effects." (PMID 38397400, 2024). "Contrary to POMC, rodent models of depression reported lower levels of NPY in plasma, cerebral spinal fluid, frontal-limbic regions, and ARC." (PMID 38263257, 2024). "In this study, the expression of NPY in the INF of depression cohorts was sharply reduced, agreeing with a previous report that showed decreased expression of NPY in the prefrontal cortex and hippocampus of depressed suicides." (PMID 38263257, 2024). "It is noteworthy that the NPY system is implicated in stress-related neuropsychiatric disorders such as PTSD and depression." (PMID 38994950, 2024). "Acting as an anti-stress neuromodulator, NPY has demonstrated notably diminished concentrations in the cerebrospinal fluid and plasma of individuals with depression." (PMID 37732301, 2023). "In this context, prostate cancer patients with a higher depression score had higher CD68+ tumor-associated macrophage infiltration and interleukin-6/NPY expressions." (PMID 37373115, 2023). "According to the literature on alcohol dependence and depression, NPY rs16147:T>C is key to understanding the development of depression in alcohol dependence withdrawal population." (PMID 36245887, 2022). "The results showed that the levels of NPY, T, IL-10, and IL-4 in the normal group, depression group, and DCMI group were from high to low." (PMID 35432561, 2022). "Amongst cyclic AMP (cAMP), protein kinase A, cAMP responsive element-binding, and neuropeptide Y (NPY), the role of NPY in the development of depression within the context of alcohol dependence is well-established." (PMID 36245887, 2022). "Conversely, administration of NPY have anti-stress effects, and thereby can reduce emotional responses on depression." (PMID 36245887, 2022). "Another group of researchers have described that those individuals experiencing the duo, i.e., PD and depression at the same time, exhibited a marked upsurge in the NPY levels within their CSF in comparison to individuals experiencing depression alone." (PMID 35562956, 2022).
depression (continued). "CC homozygotes of NPY rs16147:T>C exhibited less depression when exposed to low alcohol dependence, but more depression when exposed to high alcohol dependence." (PMID 36245887, 2022). "Interaction between NPY rs16147:T>C and alcohol dependence on depression during acute alcohol dependence withdrawal." (PMID 36245887, 2022). "The levels of IL-4, IL-10, T, and NPY in depression patients, DCMI patients, and CUMS + LPS model rats elevated, while the levels of IL-1β, IL-6, and TNF-α were reduced." (PMID 35432561, 2022). "Patients with depression had lower levels of NPY in plasma compared to controls, whereas female patients had significantly higher levels of NPY than male patients." (PMID 35680922, 2022). "We firstly identified the relevance between the NPY rs16147:T>C × alcohol dependence and depression, then competitive model-testing analysis was employed to evaluate which gene and disease interaction model was the best fit for the data." (PMID 36245887, 2022). "Many studies have shown that the expression level of NPY in the brain is closely related to the occurrence of depression." (PMID 36245887, 2022). "The present study aims to understand the role of NPY rs16147:T>C on depression in patients with acute alcohol dependence withdrawal." (PMID 36245887, 2022). "Previous work has found low levels of NPY expression in cortical brain regions of humans with a history of depression and death by suicide." (PMID 35800635, 2022). "Consistent with clinical work, preclinical studies report decreased cortical NPY, and Y1 receptor gene and protein levels expression in animal models of depression." (PMID 35800635, 2022). "NPY administered intranasally shows promising results in the therapy of depression in humans and in animal experiments, including stress experiments." (PMID 36532718, 2022). "A meta-analysis of the studies conducted among patients with major depressive disorder (MDD) confirmed that NPY levels are decreased in this disease." (PMID 33670342, 2021). "Many researchers regard neuropeptide systems (corticotropin-releasing factor, neuropeptide Y, galanin, vasopressin, substance p, somatostatin, etc.)as modulators of the behavioral states observed in mood disorders such as depression." (PMID 33436036, 2021). "NPY mRNA expression in the NAc and hippocampus of Flinder-sensitive line rats, a genetic animal model of depression, was significantly decreased compared to control Flinder-resistant line rats." (PMID 34298907, 2021). "Depression has been recently demonstrated to induce neuropeptide Y expression by PCa cells through sympathetic activation, resulting in IL-6 release from TAMs and subsequent intratumoral MDSC infiltration." (PMID 33800156, 2021). "A Chinese study also found that when a patient suffered from depression and insomnia, the level of neuropeptide Y in the body was lower than that of healthy people, and the level of substance P was higher than that of healthy people." (PMID 34046726, 2021). "On the contrary, lower levels of acylated ghrelin (IgM class) autoantibodies and lower levels of NPY (IgG class) autoantibodies in depressive disorder, a common comorbidity of eating disorders, were found." (PMID 33953692, 2021). "Injecting NPY and/or NPY receptor antagonists into mouse brains has revealed the significance of NPY in depression." (PMID 32246073, 2020). "Although the interacting mechanisms among ghrelin, neurotensin, and NPY in AD-related depression remain to be examined, neurotensin and NPY, at least, seem to be mediating some AD-related depression-like behaviors by interacting with ghrelin." (PMID 33071750, 2020). "Another investigation indicated decreased NPY plasma concentrations in patients with major depressive disorder compared to healthy controls." (PMID 33192409, 2020). "Lower plasma levels of NPY have been associated with PTSD and major depressive disorder, both of which have a higher prevalence in females." (PMID 32867327, 2020).
depression (continued). "The behavioral correlate of FSL with depression and its sexual dimorphic NPY expression suggest that depressed and depression-resilient females have less NPY than their respective males." (PMID 32867327, 2020). "Other neuropeptides, including neurotensin and neuropeptide Y (NPY), have been shown to be involved in the pathogenesis of depression." (PMID 33071750, 2020). "The reduction of NPY in the limbic region has been reported in several models of depression including the Flinders Sensitive Line and Fawn Hooded rats as well as chronic mild stress rats." (PMID 31736656, 2019). "All those results suggest that Y2R in the mPFC is involved in the pathophysiology of depression and mediates NPY antidepressant effects in LPS rats." (PMID 31736656, 2019). "Local injection of NPY into the medial prefrontal cortex (mPFC) ameliorated the depression-like behaviors and suppressed the NLRP3 inflammasome signaling pathway." (PMID 31736656, 2019). "The reduced levels of NPY were detected in cerebrospinal fluid (CSF) of patients with major depression, reflecting disturbed synthesis, turnover or degradation of this peptide." (PMID 30863280, 2019). "NPY and its receptors are widely expressed in brain regions regulating depression and stress resilience, such as cortex, hypothalamus, and hippocampus." (PMID 31736656, 2019). "Many antidepressants increase 5-HT by inhibiting 5-HT reuptake and neuropeptide Y (NPY) mimics selective 5-HT reuptake inhibitors in a rat model for depression." (PMID 29723289, 2018). "On the other hand, NPY also ameliorates depression through mechanisms involving synaptic transmission and neuroprotection." (PMID 29643431, 2018). "In the hippocampus, NPY has robust effects, including neuroprotection and synaptic transmission, that play important roles in the pathology of several depression- and anxiety-related disorders." (PMID 29643431, 2018). "Another study found a decreased level of plasma NPY concentrations in patients with a major depressive disorder." (PMID 29751614, 2018). "Further research is needed to examine the moderating and mediating effects of BMI on depression with additional biomarkers, e.g., malondialdehyde, F2-isoprostanes, 8-hydroxy 2′-deoxyguanosine, neuropeptide Y, adiponectin, IL-6, TNF-α, and IL-17." (PMID 30524737, 2018). "In a study of Fawn Hooded rats, an animal model of depression, decreased NPY concentrations were found in hippocampus compared to control animals." (PMID 28824541, 2017). "While other studies that found a relationship between NPY and depression measured its levels in plasma or CSF of the depressed patients or animal models, in this study, NPY levels were not measured in plasma or cerebrospinal fluid of the participants." (PMID 29062372, 2017). "For example, ECS-induced reductions in depression-like behavior were found to be accompanied by normalization of BDNF and Neuropeptide Y expression in brain areas relevant to depression." (PMID 28910337, 2017). "There are a number of data indicating that NPY and its receptor ligands produced antidepressant-like effects in animal models of depression." (PMID 27975125, 2017). "The beneficial effect of NPY was also observed in the acute model of depression, likely mediated by the Y1 receptors." (PMID 28469551, 2017). "NPY has also been shown to reverse tricyclic antidepressant treatment-resistant depression induced by central administration of adrenocorticotropic hormone." (PMID 28824541, 2017). "Administration of [Leu31Pro34]NPY in olfactory bulbectomized rat model of depression reduced depressive related features in open field test." (PMID 28469551, 2017). "Observations which support the role of NPY in human depression include depressed patients and suicide attempters withlow levels of NPY in plasma and cerebrospinal fluid." (PMID 29062372, 2017).
depression (continued). "The inhibition of NPY secretion in the brain has been reported in animal models of depression, while antidepressant treatments were found to increased synthesis of NPY in the brain." (PMID 29062372, 2017). "The rs16147 SNP was associated with impaired antidepressant treatment response in patients with anxious depression, and low-expression NPY genotypes were also found to be overrepresented in subjects with major depression." (PMID 28824541, 2017). "The role of alterations in NPY genotype has been reported in patients with depressive disorders following childhood emotional maltreatment." (PMID 28582442, 2017). "Then we further analyze the difference of NPY between the subtypes of depression including PSD and MDD patients." (PMID 28082897, 2016). "The reduced protein and mRNA of NPY in MDD group were obtained in genetic rat models of depression and other clinical research, suggesting that these changes most likely are triggered by stress." (PMID 28082897, 2016). "Previous studies demonstrate that the protein of neuropeptide Y (NPY) is abnormal in depression patients, but the changes of NPY in different types of depression are unclear." (PMID 28082897, 2016). "This is the first study to explore the distinguishing function of NPY in different types of depression." (PMID 28082897, 2016). "NPY can be served as a potential anti-depressive factor and used to monitor treatment of depression by recent findings." (PMID 28082897, 2016). "Clinical and experimental investigations support that NPY is involved in the pathophysiology of depression and stroke." (PMID 28082897, 2016). "In order to explore the role of NPY in different types of depression, the partial correlations, binary logistic regression analysis and receiver operating characteristic (ROC) curve were calculated for PSD and MDD groups." (PMID 28082897, 2016). "It has been reported that acupuncture acts on depression by enhancing neuropeptide Y (NYP) in the hypothalamus and amplifying neural progenitors (ANPs) proliferation, as well as preserving quiescent neural progenitors (QNPs) from apoptosis." (PMID 27680977, 2016). "Both functional analysis and genetic studies have shown that NPY is a crucial modulator of mental and emotional resilience, including depression." (PMID 25918722, 2015). "In our study, STSC and EC mice show up-regulated the expression of NPY, which is similar to previous reports in rodent models that confirm the role of NPY in coping with stress after being treated with antidepressant medication for depression and PTSD." (PMID 26016844, 2015). "Multiple rodent models of the NPY system have been used to investigate the role of NPY in depression and schizophrenia." (PMID 25762938, 2015). "The hippocampus and PFC have lower levels of both the “long” and the “short” NPY mRNAs, while only the “short” NPY mRNA was demonstrated to be downregulated in depression-like states in rat." (PMID 25918722, 2015). "Further research is needed to understand the mechanisms of depressive-like behavior from this refractory depression model, especially the implications for other subpopulations of GABAergic interneurons including somatostatin- and NPY-positive neurons." (PMID 24671607, 2014). "Most studies have found that the central NPY is insufficient in patients with depression, and that their NPY levels in plasma or cerebrospinal fluid are decreased." (PMID 23468908, 2013). "Statistical analysis showed a significant correlation between the SNP sites rs16139 in NPY and the morbidity of depression." (PMID 23468908, 2013). "A significant correlation was observed between the SNP sites rs16139 in NPY and the morbidity of depression." (PMID 23468908, 2013). "Several studies have shown that the expression level of neuropeptide Y (NPY) gene in the brain is closely related to the onset of depression." (PMID 23468908, 2013).
depression (continued). "This study aimed to investigate the single nucleotide polymorphisms (SNPs) of neuropeptide Y (NPY) and major depressive disorder (MDD) in Chinese Han population." (PMID 23468908, 2013). "In depression model rats induced by chronic unpredictable stress, many brain regions show downregulated expression of NPY, and the transgenic overexpression of NPY exerts a significant antidepressant-like effect." (PMID 23468908, 2013). "A few reports have compared NPY in plasma or cerebrospinal fluid of patients with major depression or animal models." (PMID 23468908, 2013). "Numerous studies have shown that NPY and depression are closely related with the human responses to stress." (PMID 23468908, 2013). "Notably, decreased NPY gene expression has been observed in the prefrontal cortex of humans with depression who died by suicide and in individuals with schizophrenia." (PMID 40546293, 2025). "In summary, these data point out the role of NPY in migraine and depression." (PMID 38397400, 2024). "Furthermore, it was concluded that low NPY concentrations lead to depression, and certain antidepressants seem to increase NPY levels." (PMID 38397400, 2024). "A minority (~20%) of NPY-GFP-negative NPFF-like neurons were immunopositive for cholecystokinin, a satiety-related peptide, which has also been associated with anxiety and depressive disorder." (PMID 38994950, 2024). "Moreover, a study conducted on 34 adult patients with epilepsy undergoing a temporal lobe surgery for seizure control showed a significant positive correlation of the density of NPY-positive neurons in the basolateral amygdala with depression scores." (PMID 36829752, 2023). "A study on mice used a stress-induced depression-like paradigm to demonstrate this function of NPY." (PMID 36829752, 2023). "The interaction between NPY rs16147:T>C and alcohol dependence on depression was first analyzed." (PMID 36245887, 2022). "At the same time, the levels of serum T and NPY were higher than those of patients with depression." (PMID 35432561, 2022). "Neuropeptide Y (NPY), which can maintain homeostasis from high-stress stimulation, may protect individuals from the onset of depression." (PMID 36245887, 2022). "Considering the anti-depressive potential of NPY37,38, NPY may be suggested as one of the protective mechanisms from osteoporosis in women with depression." (PMID 35680922, 2022). "Thus, the purpose of this study was to explore the interaction between alcohol dependence and NPY rs16147:T>C and its potential additional meaning in the occurrence of depression during the period of ADW." (PMID 36245887, 2022). "Furthermore, both preclinical evidence and clinical evidence showed that the low level of NPY directly led to a variety of mental illnesses, including depression and related diseases." (PMID 35432561, 2022). "For example, there is preliminary evidence of interactions between motilin and the composition of the gut microbiota and between the levels of motilin and the peptide transmitter neuropeptide Y, which has also been identified as having a protective effect against depression." (PMID 34575041, 2021). "Furthermore, the expression of the neuropeptide Y gene has been shown to be correlated with inflammation as well as social isolation and major depressive disorder." (PMID 34210304, 2021). "In contrast, in pathological conditions, such as depression, NPY release is reduced." (PMID 34305544, 2021). "Another important player in these regulations is NpY, which, beyond its main role in the control of metabolism and food intake, is also involved in stress coping strategies and in the pathophysiology of depression." (PMID 34305544, 2021). "However, these authors observed a positive association of DPP4 and depressiveness alongside an inverse correlation of NPY with increased DPP4 activity indicating their possible interaction in the pathogenesis of depression." (PMID 33192409, 2020).